ATF4 (activating transcription factor 4)
Diseases named in the same sentence as ATF4 in open-access papers (continued):
Sharing a sentence is not in itself a finding about the gene and the disease.
Obesity (52 papers, 2014 to 2026). Accumulation of substantial excess body fat. "This study evaluated MEG3, FTO, and ATF4 expression in PBMCs from children with obesity and their associations with added sugar intake and lipid metabolism genes." (PMID 40806129, 2025). "Accordingly, the present study aimed to evaluate the expression of MEG3, FTO, and ATF4 in PBMCs from children with obesity and to assess their associations with added sugar intake and the expression of lipogenesis-related genes." (PMID 40806129, 2025). "CKO mice showed Wfs1 deficiency and significantly increased expression of Atf4 and Znt3 in the hippocampus, cortex, and hypothalamus, suggesting the crucial role of Wfs1 in regulation of vicious cycle of obesity and depression." (PMID 39258564, 2024). "In alignment with our data, higher gene expression levels of GRP78, CHOP, ATF4, and sXBP1 have been associated with obesity, steatosis, and mitochondrial stress." (PMID 36834782, 2023). "Results from animal model research suggests that ATF4 is functionally associated with obesity, glucose homeostasis, fat storage, and energy expenditure during fly and mouse development." (PMID 29180630, 2017). "To confirm the causal role of the ATF4 branch of the ER stress pathway in impairing macrophage efferocytosis in vivo, we turned to the mouse model of obesity, which displays lipid accumulation, activation of ER stress, and defective efferocytosis in peritoneal macrophages as compared with lean mice." (PMID 41186004, 2025). "Here, we report that ALKBH5 (AlkB Homolog 5) and FTO (FTO: Fat mass and obesity-associated protein), the two RNA demethylating enzymes, promote the translation of ATF4 mRNA in a transformed liver cell line (Hep3B) treated with the chemotherapeutic drug sorafenib." (PMID 39199320, 2024). "The mRNA expression of SREBP1 (p = 0.0176), FASN (p = 0.0412), ACACA (p = 0.0255), FTO (p < 0.0001), and ATF4 (p < 0.0001) was significantly reduced in the obesity group compared to the control group." (PMID 40806129, 2025). "Our findings indicate that the expression of MEG3, FTO, and ATF4 is altered in children with obesity." (PMID 40806129, 2025). "For instance, using salubrinal to enhance the expression of p-eIF2α and ATF4 mitigates obesity-induced hepatic steatosis in mice." (PMID 39910053, 2025). "The WFS1/activating transcription factor 4 (ATF4)/zinc transporter 3 (ZNT3) signaling axis is implicated in palmitate-induced apoptosis, which is associated with obesity and depression, and the drug riluzole can target this axis to maintain zinc homeostasis." (PMID 41359105, 2025). "Long non-coding RNAs, particularly MEG3, are involved in obesity through regulation of lipogenic genes including ATF4, FTO, SREBP1, FASN, and ACACA." (PMID 40806129, 2025). "The activation of ATF4 in adipose tissue (AT) and brown AT similarly improves obesity and glucose intolerance." (PMID 38474243, 2024). "The regulation of ALT2 expression by the transcription factor ATF4 underscores its significant role in the metabolic adaptation in obesity." (PMID 39452573, 2024). "Reduced insulin content and increased intracellular proinsulin, as well as increased Atf4 and Chop message RNA and sXBP1 protein levels in islets from db/db mice also suggest increased ER stress in T2D/obesity." (PMID 35180212, 2022). "ATF4 regulates age-related and diet-induced obesity as well as glucose homeostasis in mammals and has conserved metabolic functions in flies." (PMID 35681299, 2022). "Deletion of ATF4 from hypothalamic POMC neurons protects mice from obesity, glucose intolerance, and leptin resistance during HFD feeding." (PMID 36188456, 2022). "Analysis of subcutaneous adipose tissue samples revealed that the mRNA expression levels of ER stress markers (Xbp1, sXbp1, Atf6, Atf4, and Grp78) were significantly higher in the hypertrophic obesity mice than in the control mice." (PMID 36035215, 2022).
Obesity (continued). "ATF4 knockout was found to protect against diet-induced obesity, hypertriglyceridemia, and hepatic steatosis by significantly decreasing the expression of lipogenic genes, such as PPARγ, SREBP-1c, and FASN." (PMID 34237916, 2022). "The mRNA expression levels of ER stress markers (Xbp1, sXbp1, Atf4, Atf6, and Grp78) were significantly higher in the ASCs treated with hypertrophic obesity adipocyte-derived EVs than in the ASCs treated with control adipocyte-derived EVs." (PMID 36035215, 2022). "The results revealed that 18 of the DMR genes were associated with addiction and obesity (ADCY3; ADCY9; ATF4; CDK5R1; CHRNB2; GABRD; GABRG3; GNB1; GNB3; GRK5; HDAC4; HDAC9; MAP2K1; PDE11A; PDE2A; PDE3A; PPP1CA; SLC6A3)." (PMID 34389046, 2021). "Given their relevance in the context of obesity, we next analyzed the expression of the genes encoding ER stress markers ATF4 and C/EBP homologous protein (CHOP) (ATF4 and DDIT3)." (PMID 32512939, 2020). "A previous study demonstrated that activation of the PERK-eIF2α-ATF4-CHOP pathway contributed to obesity-induced tubular epithelial cell apoptosis." (PMID 33384598, 2020). "Atf4−/− mice exhibit a lean phenotype and resistance to diet-induced obesity, with lower levels of circulating carbohydrates." (PMID 28860159, 2017). "Elimination of autophagy selectively in muscle reduces diet-induced obesity and insulin resistance by promoting ATF4-mediated induction of FGF21 expression." (PMID 28860159, 2017). "There is also evidence that ATF4 regulates obesity, energy expenditure, and glucose homeostasis, in that ATF4-null mice are lean and mildly hypoglycemic and resist obesity induced by aging or high energy diets." (PMID 25156122, 2014). "Interestingly, ATF4 was also proposed as a conserved regulator of cellular metabolism and carbohydrate homeostasis as ATF4-null mice are lean and resist diet-induced and age-induced obesity and diabetes." (PMID 39665647, 2025). "Additionally, when stratified by sex, girls with obesity showed lower ATF4 expression compared to girls and boys with normal weight, while boys with obesity exhibited decreased expression compared to boys with normal weight." (PMID 40806129, 2025). "Based on previous studies, Mice completely knocked out for ATF4 showed resistance to age-induced and high-fat diet-induced obesity, accompanied by reduced production of apolipoprotein and VLDL in the liver, resulting in an obstruction of the outward transport of lipids in the liver." (PMID 41031795, 2025). "ATF4-null mice were protected from age-related and diet-induced obesity and steatosis." (PMID 38216941, 2024). "ATF4 KO mice are lean and resistant to high-fat diet-induced obesity." (PMID 38474243, 2024). "In the present study, we demonstrated that long-term obesity induced ER stress, mainly via the ATF4-CHOP axis, in the hippocampal DG, leading to a decrease in the number of processes on Dcx-expressing immature neurons due specifically to the loss of Dcx mRNA stability." (PMID 35046482, 2022). "Besides, dorsomedial nucleus NPY knockdown mice showed increased basal and obesity-induced decrease in bone mineral density (BMD) together with reduced activating transcription factor 4 (ATF4) expression level." (PMID 35273572, 2022). "Furthermore, hypothalamic POMC neuron-specific ATF4 knockout protects DIO mice from obesity by increasing BAT thermogenesis and increasing oxygen consumption." (PMID 36188456, 2022). "A report shows that whole-body Atf4-KO mice are resistant to age-related and diet-induced obesity because of the reduction in the mammalian target of rapamycin (mTOR) signaling and expression of the gene that regulates the intracellular concentration of amino acids." (PMID 34547510, 2021).
Obesity (continued). "Hypothalamic pro-opiomelanocortin neuron (POMC)–specific Atf4-KO mice are resistant to high-fat diet–induced obesity via enhanced autophagy-related 5-dependent autophagy and α-melanocyte–stimulating hormone production, suggesting that ATF4 in POMC neurons negatively regulates energy expenditure." (PMID 34547510, 2021). "Several genes among this gene set were associated with obesity, including GNPDA2, MTHFR, and ATF4." (PMID 29854750, 2018). "In addition, phosphorylated PERK by GRP78 plays a role in obesity and diabetes through the eIF2α-ATF4-CHOP pathway." (PMID 29849883, 2018). "Activating transcription factor 4 (ATF4) is constitutively expressed in a variety of tissues, and regulates several pathological features associated with metabolic diseases such as non-alcoholic fatty liver diseases (NAFLD) and obesity." (PMID 29180630, 2017). "The protein expression of GRP78‐PERK‐EIF2α‐ATF4‐CHOP, the UPR sensors, was significantly higher in obesity F0 and their F1‐F2 female mice than CD mice." (PMID 40041941, 2025). "PTP1B silencing in experimental mice similarly prevented obesity-induced ER stress by inactivating CHOP, BIP, GRP94, ATF4 and XBP1 factors." (PMID 37020593, 2023). "In the present study, the expression levels of GRP78, ATF4, and CHOP were upregulated, and the phosphorylation of PERK was increased, in the livers of mice with HFD-induced obesity, which were reduced by both HIIT and MICT training for 8 weeks." (PMID 35315506, 2022). "ER stress responses in adipose tissue are a key factor in the aggravation of obesity-related problems, and PERK-eIF2α-ATF4 signaling is most important." (PMID 34768813, 2021). "Nonetheless, FGF21 was dispensable for the resistance to diet-induced obesity (DIO) and IR observed in these mice, which were mediated by alternative mechanisms downstream of ATF4." (PMID 33944779, 2021). "To investigate the relationship between adipsin expression and ER stress in the context of obesity, we first examined mRNA expression of adipsin and ER stress markers such as CHOP, ATF4, and GRP78 in the adipose tissues (gWATs) of genetically obese db/db mice." (PMID 32079203, 2020). "We demonstrated that ATF4 overexpression is sensitive to HFD-induced adipocyte hyperplasia, which, at least partially, accounts for the weight gain or obesity in ATs − Dox." (PMID 29180630, 2017). "For ATF4, boys with obesity showed lower expression than boys without obesity (p = 0.036) and girls without obesity (p < 0.001)." (PMID 40806129, 2025). "Interestingly, we observed a significant positive correlation between ATF4 and SREBP1, FASN, and ACACA expression in PBMCs from children with obesity." (PMID 40806129, 2025). "In contrast, a previous study reported no changes in ATF4 expression in women with obesity compared to those with normal weight." (PMID 40806129, 2025). "Evidence suggests that obesity induces ER stress in the hearts of mice, as shown by the upregulation of eIF2α (eukaryotic initiation factor 2, α subunit), GRP78 (Glucose-regulated protein, 78 kDa), and ATF4 (activating transcription factor 4)." (PMID 40004130, 2025). "Regarding ATF4 gene, our results showed decreased expression in PBMCs from children with obesity compared to those without obesity." (PMID 40806129, 2025). "We provide insight into the expression of the ISR member ATF4, as well as its target genes within multiple PVAT depots that will inform future pursuits to tackle the issue of PVAT functional disruption in the context of obesity." (PMID 41420377, 2025). "However, mechanisms independent of FGF21, but dependent on ATF4 induction, promote resistance to diet-induced obesity in OPA1 BAT KO mice." (PMID 33944779, 2021).
Obesity (continued). "Altered DNA methylation in promoters of transcription factor genes (PPARA, KLF15, NR3C1, RORA and ATF4) known to regulate FGF21 expression and its binding receptors and co-factors (FGFR1, FGFR3 and FGFRL1 and KLB) has been revealed in relation to the elevated levels of circulating FGF21 in obesity." (PMID 33670024, 2021). "Mice lacking ATF4 are lean and resist diet-induced obesity, although they have adipose tissue." (PMID 26111340, 2015). "The protein levels of p‐PERK/PERK, p‐EIF2α/EIF2α, ATF4, and CHOP were significantly raised in the liver from the HFD‐F0 mice and their F1‐F2 female offspring, suggesting that ER stress and the PERK‐p‐EIF2α‐ATF4‐CHOP pathway may contribute to the glucose metabolic dysfunction upon paternal obesity." (PMID 40041941, 2025).
glioblastoma (51 papers, 2015 to 2025). The most malignant astrocytic tumor (WHO grade IV). "ATF4 activation has been reported to increase xCT expression in glioblastoma cells, and ATF4 silencing renders tumor cells susceptible to RSL3-induced ferroptosis." (PMID 34987700, 2021). "Furthermore, ER stress is linked with reticulophagy in glioblastoma cells via ATF4, which is a key component of the UPRer pathway and ovarian follicle development." (PMID 36769070, 2023). "Recent studies have shown that the activation of GPR68 under acidic conditions activates the endoplasmic reticulum stress activating transcription factor 4 (ATF4) signaling pathway, which is a novel survival pathway in glioblastoma." (PMID 41190345, 2025). "We use U87 and U138 glioblastoma cell lines to show how selective induction of ferroptosis occurs in an ATF4-dependent manner." (PMID 38291540, 2024). "The complex interaction between LSD1 and ATF4 in maintaining formation of glioblastoma multiforme is critical for the transcriptional response of TICs to stress." (PMID 38601083, 2024). "It has been found that ATF4 plays a key role in proliferation, stemness and drug resistance of glioblastoma cells via complex mechanisms." (PMID 38601083, 2024). "Biological properties of ATF4 in glioblastoma have been extensively documented in a series of studies." (PMID 38601083, 2024). "Herein, ATF4-mediated fructolysis is an essential metabolic adaptation, indicating a promising target for the treatment of glioblastoma." (PMID 38601083, 2024). "Recent studies have shown that the transcription factor ATF4, which is accompanied by the induction of additional ER stress markers, links ER stress with reticulophagy in glioblastoma cells." (PMID 37316499, 2023). "For example, Temozolomide and Salubrinal show synergistic effects in glioblastoma cells and Salubrinal is capable of upregulating the expression of ATF4 and enhancing apoptosis induced by Temozolomide." (PMID 36677903, 2023). "Here, the authors show that glucose deprivation induces fructolysis through selective activation of ATF4 translation, thereby supporting malignant progression of human glioblastoma." (PMID 36245009, 2022). "For example, it has been reported that loperamide can induce the expression of Cyclic amp-dependent transcription factor ATF-4 (ATF4) in glioblastoma cells." (PMID 34571977, 2021). "We analyzed the impact of ATF4 knockdown on cell growth and Sunitinib treatment effects with an extended panel of BTICs and glioblastoma cell lines." (PMID 30719230, 2019). "We found that KPNB1 inhibition activated PERK/eIF2α/ATF4 signaling in both human and rat glioblastoma cells." (PMID 29520102, 2018). "First, the redox master regulator ATF4 is abundantly expressed in glioblastoma specimens and cell lines." (PMID 28881638, 2017). "ATF4 inhibition impaired fructolysis to suppress growth of glioblastoma cells." (PMID 38601083, 2024). "Previous studies have indicated that MTHFD2 can specifically regulate the PERK/ATF4 axis in glioblastoma cells, and the variation in our findings may be attributed to the differences in cell types and experimental conditions." (PMID 39247810, 2024). "In a word, ATF4 could modulate metabolic reprogramming, integrated stress response and ferroptosis to promote progression of glioblastoma." (PMID 38601083, 2024). "ATF4 links ER stress with reticulophagy in glioblastoma cell death." (PMID 36769070, 2023). "In glioblastoma multiforme, studies demonstrated that ATF4 is a novel upstream regulator of p21." (PMID 35484984, 2022). "We hypothesized that ATF4 is essential for the adaptation of human glioblastoma (GB) cells to the conditions of the tumor microenvironment and is contributing to therapy resistance against chemotherapy." (PMID 34239013, 2021). "Therefore, we concluded that the NF-κB pathway facilitates ferroptosis by downregulating ATF4 and xCT in glioblastoma cells." (PMID 34987700, 2021).